COL11A1 (collagen type XI alpha 1 chain)
Diseases named in the same sentence as COL11A1 in open-access papers (continued):
Sharing a sentence is not in itself a finding about the gene and the disease.
tumor (continued). "While the majority of these studies focused on stromal COL11A1, a few studies have shown that aggressive tumor cells driving metastasis and drug resistance also express high levels of COL11A1." (PMID 33668097, 2021). "The enhanced invasion by wild-type COL11A1 cells adjacent to mutant COL11A1 cells indicates that COL11A1 mutations observed in cSCC can increase neoplastic invasion by adjacent COL11A1 wild-type tumor cells." (PMID 34584216, 2021). "More evidence is needed to show how COL11A1 regulates biophysical properties of tumor ECM and how it affects migration of tumor and immune cells." (PMID 33668097, 2021). "Specific components of the tumor microenvironment such as COL11A1, fibroblast activation protein (α-FAP), and COX-2 have been suggested as both diagnostic/prognostic markers for the presence or progression of neoplasia and as potential therapeutic targets." (PMID 32656339, 2020). "Conversely, RNA expression of the two exemplary collagens (COl27A1 and COL11A1) was nearly restricted to tumour cells in AdCy." (PMID 32878206, 2020). "Further analysis of TMA revealed that tumor epithelial cells adjacent to COL11A1-postive stroma showed the strongest CPT1A expression." (PMID 32312965, 2020). "In the present study, over-expressed CDX2 and let-7b inhibited lymph node metastasis and tumor growth by silencing COL11A1." (PMID 31938021, 2020). "In summary, we revealed an overexpression of ECM components, which are associated with enhanced migratory capacities of tumour cells (TNC, FN1), resistance to chemotherapy (COL11A1, SPP1) and adverse outcome (COL11A1, TNC, FN1) in other primaries." (PMID 32878206, 2020). "Among them, the expression of COL1A1, COL10A1 and COL11A1 was particularly higher, and that of COL4A4, COL6A5 and COL14A1 was especially lower in tumor tissues, indicating their possible roles as diagnostic markers for ESCC." (PMID 31598423, 2019). "Using OVCAR8 xenograft specimens we confirmed the inhibitory effect of LY on TGF-β signaling and tumor stromal expression of collagen type XI chain 1 (COL11A1) and versican (VCAN)." (PMID 30087253, 2018). "Our data demonstrate that LY can delay tumor growth and ascites formation in OC xenografts and these in vivo effects are correlated with reduced-expression of important stroma-derived proteins COL11A1 and VCAN." (PMID 30087253, 2018). "Excess expression of both Collagen (COL11A1, COL7A1) and Integrin (ITGA2) is known to be associated with cell invasiveness and tumor formation." (PMID 28821810, 2017). "A cut-off value of 1.8 was used to categorize the tumours into groups with high or low COL11A1 mRNA levels." (PMID 26087191, 2015). "Increased gene expression of COL11A1 was observed in all EOC patients during tumor progression and was greatly increased in metastases." (PMID 26579497, 2015). "The most significant associations were for COL11A1 and ITGAX with tumor stage in GNCA, and UNG with metastasis, also in GNCA." (PMID 23717493, 2013). "miR-139-5p suppresses COL11A1 expression, leading to reduced tumor cell proliferation." (PMID 41462920, 2025). "The specific composition of the breast stroma, together with tumor microenvironmental heterogeneity and immunological variation among molecular subtypes, may influence the signaling pathways activated by COL11A1." (PMID 41462920, 2025). "Interestingly, cluster 1, which had the highest proportion of cells from primary tumor sites among the metastatic clusters, showed enrichment of myCAFs and activated COL11A1, suggesting molecular myCAF/OSCC crosstalk though the ECM-CD44 axis." (PMID 40906645, 2025).
tumor (continued). "COL11A1 provides valuable information about the tumor microenvironment and may assist in: confirming stromal invasion in diagnostically uncertain cases (e.g., DCIS or ADH), assessing recurrence risk, and evaluating response to antistromal therapies." (PMID 41462920, 2025). "Accordingly, a significant reduction in collagen type XI alpha 1 (COL11A1) levels could also be observed in BBIT20-treated tumours, a collagen subtype typically overexpressed in PDAC that is associated with tumour progression, metastasis and poor prognosis." (PMID 40275348, 2025). "COL11A1 protein staining revealed a dense network of collagen fibers aligning the basement membrane of tumor nests, indicating that mCAFs may control T cell marginalization as has been shown for COL11A1 expressing CAFs in lung cancer." (PMID 39516494, 2024). "High level of COL11A1 promotes tumor cell proliferation, migration and metastasis." (PMID 38806505, 2024). "Taken together, these studies reaffirm our bioinformatics-based analysis and suggest that these extracellular matrix genes (CDH3, COL11A1, COL1A1, COL17A1, KRT19, ITGA2, LAMC2, and SULF1) are highly associated with PDAC tumor carcinogenesis and peritoneal metastasis." (PMID 39682235, 2024). "Compared to the control group, COL11A1 knockdown markedly retarded the growth of xenograft tumors throughout the entire treatment period, as evidenced by the reductions in tumor volume and tumor weight." (PMID 38806505, 2024). "VCAN1, EDB, and COL11A1 were expressed in >50% of tumor cells in 8 or 9/15 PDX samples." (PMID 38702309, 2024). "Our results showed that COL11A1+ FBs specifically exist in tumor tissues, thus could be considered as CSFs." (PMID 36744260, 2023). "Bioinformatic analyses revealed five major cell types based on hallmark gene expression: myeloid (Cd11b; 12 clusters), lymphoid (Cd33/Ncr1/B220/Cd19; 5 clusters), tumor (Olig2/Cd276/Col11a1; 1 cluster), endothelial (Enpp2; 1 cluster) and fibroblast (plp1/Ptgds; 1 cluster) cells." (PMID 37333156, 2023). "siRNA-mediated silencing of COL11A1 decreases tumor formation and lung colonization." (PMID 38264664, 2023). "In CRC, high expression of COL11A1 was not only positively correlated with the tumor stage but also with the malignant behavior of CRC, and miR‐339‐5p could down‐regulate COL11A1 expression and inhibit colorectal progression." (PMID 36999888, 2023). "COL11A1 expression was observed as cytoplasmic staining in fibroblasts surrounding the tumor." (PMID 37760937, 2023). "In the current study, we observed COL11A1 expression in the ACC tumor parenchyma." (PMID 37509222, 2023). "Bioinformatic analyses revealed five major cell types based on hallmark gene expression: myeloid (Cd11b; 12 clusters), lymphoid (Cd33/Ncr1/B220/Cd19; five clusters), tumor (Olig2/Cd276/Col11a1; one cluster), endothelial (Enpp2; one cluster), and fibroblast (plp1/Ptgds; one cluster) cells." (PMID 37971169, 2023). "The present work shows how COL11A1 expression is a solid predictive marker of tumor infiltration." (PMID 37760937, 2023). "The use of COL11A1 as a tumor invasiveness marker presents some advantages over other markers." (PMID 37760937, 2023). "Furthermore, we performed IHC staining to examine the expression of COL11A1 in clinical BCa samples and verified the specific COL11A1 expression in tumor stroma." (PMID 36744260, 2023). "However, miR-509-3p expression was positively correlated with the COL11A1 level in EOC tumor samples and cell lines." (PMID 37386587, 2023). "Interestingly, COL11A1 (collagen type XI alpha 1 chain) was shown to be highly expressed by CAFs and tumor cells in patient samples." (PMID 36231134, 2022). "During the cultivation of PANC-1 cells transfected with pCMV3-COL11A1, we found that these cells exhibited a more spindle-like cell shape with more pseudopods, indicating that COL11A1 might mediate morphological changes with EMT features in tumor cells." (PMID 35327583, 2022).
tumor (continued). "Together, miR-339-5p repressed tumor cell functions through COL11A1 downregulation." (PMID 35669376, 2022). "Interestingly, the mode of COL11A1 production was nearly mutually exclusive as only 4% of the tumours exhibited both CAFsCOL11A1 and TCCOL11A1." (PMID 34378164, 2022). "However, little is known about the specific mechanism through which COL11A1 regulates tumor progression." (PMID 35847935, 2022). "Furthermore, we evaluated the possible link between the ECMGs and the tumor stage of PAAD, and 8 ECMGs (i.e. FN1, LAMA3, ITGB6, ITGB4, ITGA2, LAMC2, COL11A1, LAMB3) were detected to be significantly associated with tumor stage." (PMID 36311789, 2022). "In fact, only one endometrial and one OC displayed tumour cell based COL11A1 production." (PMID 34378164, 2022). "Moreover, the expression of ACTA2, ASPN and COL11A1 genes are reduced in fibroblasts after cultivation with tumor cells." (PMID 36263012, 2022). "Furthermore, both GEO datasets, GSE42568 and GSE 109169, also confirmed that the expression of COL11A1 was higher in the tumor compared to normal tissues." (PMID 36389832, 2022). "Preliminary data also suggests that a COL11A1-expressing CAF subset may also promote T cell exclusion from the tumor microenvironment." (PMID 36404344, 2022). "In addition, LY2157299 has blocked TGF-β1-induced fibroblast activation and inhibited the expression of COL11A1 in tumor stroma." (PMID 35847935, 2022). "However, the specific molecular mechanism of how COL11A1 participates in immune cell regulation in tumor microenvironment still needs to be further explored and verified by biological experiments." (PMID 36160004, 2022). "More recently, we identified a novel role of COL11A1 in modulating tumor cell metabolism." (PMID 33668097, 2021). "We also observed that the prominence of this co-expression signature varied significantly among the tumor samples, having only hints of their presence in some of them, suggesting that the corresponding patients were at various stages of the generation of COL11A1-expressing CAFs." (PMID 34283835, 2021). "Finally, rescue experiments validated the fact that circ-0005105 accelerates PDAC tumor growth and metastasis potential by targeting the miR-20a-3p–COL11A1 axis." (PMID 34183642, 2021). "In addition, there was a significant positive correlation between COL11A1 and tumor proliferation markers (Ki-67 and PCNA) expression levels." (PMID 34183642, 2021). "Whether COL11A1 originated from stromal cells activates different signaling compared to tumor cell intrinsic COL11A1 is still unclear." (PMID 33668097, 2021). "Patients expressing high levels of COL11A1 could be treated by pharmaceutical inhibitors blocking COL11A1 signaling to attenuate tumor cell chemoresistance and recurrence." (PMID 33668097, 2021). "COL11A1 expression levels were higher in PDAC tissues than in the non-tumor counterparts." (PMID 34183642, 2021). "Tumor cells were likewise decreased in nude mice inoculated with shRNA against COL11A1, where the positive metastasis rate was 25% as 2 out of 8 nude mice presented positive lymph node metastasis compared to NC of shRNA against COL11A1." (PMID 31938021, 2020). "It has been reported that COL11A1 promotes tumor progression in EOC via ECM-receptor interactions." (PMID 30002310, 2018). "Overexpression of COL11A1 has been reported in mesenchymal derived tumours." (PMID 30517191, 2018). "Knockdown of COL11A1 reduces migration, invasion, and tumor progression in mice." (PMID 27843486, 2016). "COL11A1 mRNA expression levels in tumours were evaluated by real-time RT-PCR." (PMID 26087191, 2015). "However, unlike PD-L1, whose expression is heterogeneous and dynamic, COL11A1 may reflect a more stable marker of aggressive tumor behavior and tumor stroma immune interactions." (PMID 41462920, 2025). "Additionally, we assessed the percentage of tumour cells with COL11A1 staining (TCCOL11A1)." (PMID 34378164, 2022).
tumor (continued). "When we applied the algorithm in each of the tumor samples, we found a set of signatures that were changing in a remarkably continuous manner across the samples, some of them being very similar to those of the normal samples, while others are similar to the COL11A1-based signature." (PMID 34283835, 2021). "Therefore, the COL11A1/AktSer473/CREBSer133 cascade might represent an effective target for interfering with the tumor-permissive ECM in PDAC." (PMID 33531986, 2021). "The expression of COL11A1 in AdCy could be almost exclusively attributed to the tumour cells." (PMID 32878206, 2020). "Besides FLNC, ITGA2, COL1A1 and COL11A1 were tumor invasion and metastasis-related proteins." (PMID 27626164, 2016). "The COL11A1-related signature may be attributed to the presence of CAFs within the tumor." (PMID 27028324, 2016). "Collectively, our findings highlight the importance of COL11A1 in EOC tumour progression and chemoresistance, and suggest that future therapies targeting COL11A1 or the Akt signalling pathway might provide new opportunities for therapeutic intervention in chemoresistant EOC." (PMID 26087191, 2015). "Increased COL11A1 expression, through the regulation of TGF-β3, activates CAFs via the NF-κB/IGFBP2 axis and also affects tumor aggressiveness and therapy resistance through the TGF-β1/MMP3 axis." (PMID 40136652, 2025). "Proteins such as periostin (POSTN), versican (VCAN), collagen type XI alpha 1 (COL11A1), and collagen triple helix repeat containing-1 (CTHRC1), through TGF-β signaling, participate in CAF activation and promote tumor progression." (PMID 40136652, 2025). "These fibroblasts play a pivotal role in ECM remodeling, where high levels of COL11A1 activate TGF-β signaling, leading to CAF activation, tumor progression, and poor clinical outcomes." (PMID 40721833, 2025). "In this investigation, the focus was on the role of the TMB and COL11A1 gene in HNC and their correlation with tumor progression." (PMID 40322427, 2025). "In this study, we noticed that the promoter regions of five HGs, such as KRT19, MMP1, COL11A1, SDC1, FN1, and COL5A1 were highly methylated in normal compared to tumor patients." (PMID 38639039, 2024). "Of the primary tumors, 12/18 OS, 7/11 EWS, and 14/37 RMS samples highly expressed COL11A1; 5/18 OS, 3/11 EWS, and 10/37 RMS tumor samples showed low expression, respectively." (PMID 38702309, 2024). "COL11A1- and EDB-CAR T cells produced significant amounts of IFNγ in comparison to NT T cells only in the presence of antigen-positive tumor cells." (PMID 38702309, 2024). "On the other hand, from methylation analysis, we observed that the promoter region of HGs such as KRT19, MMP1, COL11A1, SDC1, FN1, and COL5A1 is significantly methylated in normal tissue than in tumor tissue." (PMID 38639039, 2024). "The fibrillar collagens COL2A1, COL11A1, and COL11A2 show higher expression in the solid tumour region and other fibrillar collagens, COL1A2 and COL3A1, show higher abundance in the brain/tumour interface region." (PMID 38001067, 2023). "The FAP mRNA levels showed a significant positive correlation with the ACTA2, COL11A1, TNC, and PDPN genes in PanCK(-) AOIs at EOCC tumor invasive margin." (PMID 37964075, 2023). "Second, the survival analysis showed that 7 genes had significant (p < 0.05) Kaplan–Meier curves, including 5 genes (MS4A1, N4BP2L1, IGF1R, TCF7L2 and COL11A1) based on the normal expression, and 2 genes (TCF7L1 and PTPRM) based on the tumor expression." (PMID 35406404, 2022). "sc-CAFs-NFs analysis revealed a significant increase in CAFs expression of 3 exiting marker genes (FAP, COL11A1 and POSTN) and 2 newly proposed markers (COL6A3 and MFAP2) in all tumor types we studied." (PMID 36263012, 2022). "Further evidence is needed to show how COL11A1 regulates the biophysical properties of tumor ECM and how it affects the invasion, migration, and the proliferation of tumor and immune cells." (PMID 35847935, 2022).
tumor (continued). "For example, COL11A1 was considered to be a prognostic marker of PDAC and was significantly related to tumor immune infiltration." (PMID 35425701, 2022). "For ADAMTS12, AEBP1, COL10A1, COL11A1, CXCL11, EPPK1, and WNT7B, their expression values were higher in tumor samples than in normal samples." (PMID 35505821, 2022). "WT1, COL11A1, FGF5, and IGFL2 were up-regulated in tumor tissues, while GFAP and CD300LG were down-regulated." (PMID 33987034, 2021). "The ECM-related genes, DCN, COL11A1, LAMC3, and COL25A1, were also significantly downregulated in PVTT, compared with primary tumor tissues, indicating that the ECM is involved in macrovascular invasion by HCC." (PMID 34504839, 2021). "A cluster of genes that were upregulated in the tumours, compared to normal tissues were COL1A1, COL11A1, SPP1, COMP, SFRP4 and INHBA." (PMID 34824625, 2021). "We were able to confirm the increased mRNA expression of COL11A1 and MUC16 in samples from LUAC patients compared with non-tumor lung tissue samples from the same patient." (PMID 32707902, 2020). "As ECM production by tumour cells has also been reported, we used RNA in situ hybridisation (RNA-ISH) for COL11A1 and COL27A1." (PMID 32878206, 2020). "In contrast with the human samples, ADARB1 and CCBE1 were upregulated and COL11A1 and MUC16 were downregulated in FGF14 overexpressing xenograft tumors, which emphasized the tumor suppressing role of FGF14 in NSCLC." (PMID 32707902, 2020). "In univariate analysis, larger tumour size, with pharmaceutical drug adjuvant therapy, high FNCLCC grade, increased COL11A1, ITGA10 and KIF26B expression, and decreased CLEC3B, DUOX2, KRT75 and PPP2R2B were risk factors of shorter RFS." (PMID 31742892, 2020). "The mRNA expression of CCBE1 and ADARB1 was significantly upregulated, while the expression of COL11A1 and MUC16 was significantly downregulated in LUAC samples compared with non-tumor samples." (PMID 32707902, 2020). "The genes COL11A1 and COL1A1 are upregulated by miRNAs across five tumor entities (BRCA, LUAD, STAD, HNSC, and LUSC) and zebrafish samples (4, 7, and 14 dpi)." (PMID 33362851, 2020). "Our previous report also indicated that COL11A1 promotes tumor aggressiveness via the TGF-β1–MMP3 axis, and that a NF-YA-binding site on the COL11A1 promoter is the major determinant of TGF-β1-dependent COL11A1 activation." (PMID 30975980, 2019). "We further showed that COL8A1 and COL11A1 are expressed by some HNSCC cell lines and are expressed by both tumour cells and CAFs in HNSCC tissues." (PMID 31717573, 2019). "In total, we quantified approximately 4200 proteins and found that mucinous (e.g. MUC1 and MUC2) and mesenchymal proteins (such as THBS2, COL11A1, and CTHRC1) were significantly upregulated in the primary tumor compared to healthy surrounding tissue." (PMID 29901861, 2018). "In our previous study, THBS2, COL11A1 and VACN were also identified as up-regulated genes in NSCLC compared with adjacent non-tumor tissues through integrated analysis of microarray data." (PMID 28881680, 2017). "Our data also demonstrates significant up-regulation of COL11A1, COL10A1, MMP1 and MMP13, and significant down-regulation of COL6A6 and DLK1 in tumor relative to non-tumor adjacent breast tissue." (PMID 27857161, 2016). "COL11A1, COL10A1, MMP1 and MMP13 are highly expressed in aggressive molecular subtypes (basal and HER2 tumors) in the Lebanese as their expression increases tumor migration and proliferation." (PMID 27857161, 2016). "In addition, we demonstrated that the ITGA11+ myCAF subgroup produced a cascade signalling under TGF‐β/TGFR activation and highly expresses ECM‐related genes such as COL11A1 and MMP11, assisting tumor cells in initiating the metastatic program." (PMID 41017455, 2025). "CD36, highly expressed in LN-CAFs, may support lipid metabolism-driven tumor survival in metastatic lymph nodes, whereas COL11A1, elevated in Lung-CAFs, likely enhances ECM remodeling at the primary tumor site." (PMID 40940956, 2025).